AKT2 (AKT serine/threonine kinase 2)
Diseases named in the same sentence as AKT2 in open-access papers (continued):
Sharing a sentence is not in itself a finding about the gene and the disease.
tumor (continued). "In addition, AKT2 was associated with tumorigenesis of GC, and AKT2 knockdown can inhibit the proliferative potential of tumor cells." (PMID 34548487, 2021). "Transient as well as stable silencing of Akt2 resulted in a strong inhibition of Rb phosphorylation associated with a decrease in cellular proliferation and colony formation, leading to the inhibition of tumor growth in the xenograft model." (PMID 26234648, 2015). "Another explanation for having metastasis in tumours with active Wnt pathway might be the involvement of another mutation that affects the akt1 or the akt2 gene." (PMID 26528548, 2015). "This study aimed to investigate the frequency and distribution of AKT2 variants in a cohort of Jordanian men diagnosed with PC and to evaluate the relationship between these genetic variations and clinicopathological parameters, including age, tumor stage, PSA levels, and Gleason score." (PMID 42196210, 2026). "Indeed, while the inhibition of Akt1 was significantly linked to the reduced proliferation and tumor progression of in vivo OC cells, the silencing of Akt2 increased the tumor growth, and Akt3-KO mice displayed an intermediate phenotype, leaning towards the stimulation of OC cell growth." (PMID 38929705, 2024). "Increasing studies demonstrate the role of AKT2 in cancers as an oncogene which is closely associated with tumor aggressiveness by enhancing cancer cell survival, migration and invasion However, miR-497/AKT2 axis in non-small cell lung cancer (NSCLC) remains unclear." (PMID 33015042, 2020). "Furthermore, in our cohort, higher levels of AKT2 were associated to lower tumor grade BC." (PMID 31781306, 2019). "Its target genes are involved in the regulation of G0 to G1 transition, in the inner mitochondrial membrane organization and membrane potential, as well as increased tumor latency, and AKT2 was one of its many predicted targets (−53691, TSS)." (PMID 40565279, 2025). "Specifically, Akt2 signaling in CTLs accelerated effector functions, leading to a rapid attack on tumor cells." (PMID 40139836, 2025). "These Akt2-OE CTLs showed a greater capability to proliferate, to release cytokines and to kill tumor cells in comparison with Akt1-OE or control CTLs." (PMID 40139836, 2025). "In PC genetically engineered mouse models, AKT1 is responsible for primary tumor growth, whereas AKT2 promotes the development of distant metastasis and disease aggressiveness." (PMID 39980141, 2025). "Similar results are observed in human NF1 tumors with high concordance of GLUT1 and Akt2 within tumor macrophages." (PMID 40279245, 2025). "In line with the tumor growth curves, immunohistochemical staining of Ki67, a proliferation marker, demonstrated the growth-promoting effect of AKT2-206 in the presence of PLX4032." (PMID 40681872, 2025). "Tumors of mice receiving Akt2-OE CTLs exhibited both tumor cell apoptosis and substantial macrophage infiltration (cleaved caspase 3 and F4/80 staining in brown), in contrast to the other groups." (PMID 40139836, 2025). "Functionally, ectopic expression of AKT2-206 conferred MAPKi resistance in sensitive cell lines, while knockdown of hnRNPK enhanced the sensitivity of tumor cells to MAPKi." (PMID 40681872, 2025). "We then sought to elucidate the regulatory mechanisms that perturb BRAFi sensitivity in tumor cells by controlling the splicing switch of AKT2." (PMID 40681872, 2025). "Histological examination of liver/tumor tissues revealed extensive infiltration of mononuclear cells in tumors of mice receiving Akt2-OE CTLs, while tumors of mice receiving control or Akt1-OE CTLs showed fewer mononuclear cells." (PMID 40139836, 2025).
tumor (continued). "In Ag- HCC mice, Akt2-OE CTLs showed minimal proliferation and expansion in tumor, spleen, or lymph nodes across all time points." (PMID 40139836, 2025). "Akt2 signaling, in particular, accelerates these effector functions for a rapid attack on tumor cells." (PMID 40139836, 2025). "Studies increasingly show that the tumor-aggressive oncogene AKT2 leads to cancer cell invasion, migration, and survival." (PMID 38577021, 2024). "The experimentalfindings indicated that AKT2/p-AKT/RhoB proteins played a crucial role inprolonging the survival cycle of tumor-bearing hosts." (PMID 38775545, 2024). "In cancer cells, AKT1 is involved in proliferation and growth, promoting tumor initiation and suppressing apoptosis, whereas AKT2 regulates cytoskeleton dynamics, favoring invasion and metastasis." (PMID 39796647, 2024). "miR‐148a targets AKT2, inhibiting its expression and activity, subsequently suppressing the activation of downstream mTOR, ultimately leading to the inhibition of tumor cell growth." (PMID 39092291, 2024). "Specifically, AKT2 exhibited significant overexpression in tumor tissue (p = 0.01), while AKT2, AKT3, PPARG, and PTEN displayed significant increases in normal tissue (p ≤ 0.04)." (PMID 38505269, 2024). "Using genetically engineered mouse models and tetracycline-regulated AKT isoform shRNA, it was found that in prostate cancer, AKT1 promotes tumor growth, and AKT2 promotes metastasis." (PMID 39614261, 2024). "The latest research has shown AKT2 as an oncogenic gene that fosters cancer cell longevity and invasion, contributing to tumor aggressiveness." (PMID 38577021, 2024). "Our study suggests that circ_0000118 functions as a tumor-promoting molecule in CC by modulating miR-211-5p/miR-377-3p/AKT2 axis." (PMID 36719624, 2023). "This miRNA acts as a tumor suppressor gene by targeting DNMT3B, Bcl-2, PI3KR1, and AKT2, which radiosensitize the tumor by regulating DNA damage." (PMID 37958993, 2023). "AKT1, as a growth inducer, promotes tumour cell growth but damages metastasis, while AKT2 can increase tumour cell invasion and metastasis." (PMID 37489050, 2023). "The data presented in this report provide strong evidence that the key limiting event regulated by AKT2 was tumor cell extravasation." (PMID 37894325, 2023). "In contrast, treatment with the combination of p110β/AKT2 inhibitors showed statistically significant tumor suppression over controls." (PMID 37292818, 2023). "AKT2 knockdown significantly slowed tumor growth relative to the control mice fed with regular chow, but tumors eventually grew in both groups despite persistent AKT2 knockdown in the majority of tumors." (PMID 37894325, 2023). "In tumor tissues, seven gene amplification mutations included CDK4 (Mutation abundance, MA:1.57), AKT2 (MA:1.65), CCND2 (MA:1.63), MDM2 (MA:1.57), NTRK1 (MA:2.38), AXL (MA:1.65), and KRAS (MA:1.63), as well as the AFF3 gene missense (c.1781_1787del insC)." (PMID 37089080, 2023). "Fifth, it has been demonstrated that inhibiting both AKT1 and AKT2 is essential for obtaining a greater sensitization of tumor cells to apoptotic stimuli and reduceing AKT phosphorylation in vivo." (PMID 37513905, 2023). "The PI3K/Akt pathway can be activated in tumor cells through mutations or amplification of PIK3CA, loss of PTEN function and/or overexpression of Akt1, Akt2 and Akt3." (PMID 36291790, 2022). "The transfer of CAFs to Gln-rich areas is mediated by a polarized protein kinase B (AKT2), and the presence of polarized AKT2 recruits the aggression of CAFs and the absconds of cancer cells from original tumor sites." (PMID 36046791, 2022). "Inhibition of PI3K, siRNA-mediated Akt2 depletion and mtDNA reconstitution were sufficient to restore the sensitivity of tumor cells to anoikis and reduce their migration." (PMID 35454769, 2022).
tumor (continued). "The AKT2 oncogene can be amplified in ovarian, endometrial, pancreatic and other cancer types, while the ARID1 tumor suppressor commonly bears truncating mutations in many cancers." (PMID 35614096, 2022). "MiR-124-mediated AKT2 suppression led to a significant reduction in the tumor size, tumor weight and the number of microvessels, thus suppressed ER-positive BC angiogenesis in vivo." (PMID 35499045, 2022). "Intriguingly, the differential expression of AKT3 was unique as its two closely related AKT family members, AKT1 and AKT2, were found to be similarly expressed across all CMSs in cell lines and tumours." (PMID 33673003, 2021). "A recent study revealed a completely different picture of how Akt1 and Akt2 contribute to tumor development and metastasis based on systemic versus autonomous deletion of Akt1 and Akt2." (PMID 34298660, 2021). "Previous evidence has illuminated that AKT2 was targeted and negatively mediated by miR-194, and the upstream lncRNA SOX2OT served as a miR-194 sponge to upregulate AKT2, intensifying tumor growth and metastasis of GC30." (PMID 34548487, 2021). "Several studies showed that Akt1 and Akt2 have opposite effects on tumor initiation and tumor progression." (PMID 34298660, 2021). "Activated Akt2 in the same model system did not affect tumor development but caused a substantial increase in lung metastases, supporting the notion that Akt1 and Akt2 have distinct effects on tumor initiation versus tumor progression." (PMID 34298660, 2021). "It is worth mentioning that mining the data from the TargetScan database, the tumor suppressor miR-637 has other Akt isoforms as gene targets like Akt2 and Akt3 in addition to Akt1." (PMID 33911067, 2021). "In the present study, the entire expression of Akt was similar in normal and tumor tissues, whereas contrasts in p-Akt and Akt2 expression were demonstrated in different histological grades." (PMID 34359206, 2021). "In contrast, Akt2 facilitated tumor progression by increasing cell migration, invasion and metastasis." (PMID 34298660, 2021). "AKT is a serine/threonine protein kinase, also known as protein kinase B. The AKT family mainly includes Akt1, Akt2, and Akt3, among which Akt1 plays a significant role in promoting tumor cell proliferation and inhibiting tumor cell metastasis." (PMID 34484402, 2021). "For example, AKT2 ablation was shown to result in an acceleration of tumor induction in MMTV-ErbB2/neu and MMTV-PyMT transgenic mice." (PMID 33498407, 2021). "As substantial Akt1, Akt2 and Akt3 mRNA levels were detected in the majority of tumor samples of HNSCC patients, we can conclude that the target of MK2206 is present in HNSCC patients." (PMID 34568028, 2021). "We then divided the available RCC tumor samples into low versus high expression of AKT1, AKT2 and AKT3 and performed a patient survival association analysis." (PMID 34384473, 2021). "Our data have validated that KLF5 knockdown accelerated GC cell autophagy in vitro and repressed tumor growth in vivo by regulating the DANCR/miR-194/AKT2 axis." (PMID 34548487, 2021). "Cell-autonomous Akt2 ablation inhibited primary tumour formation whereas germline or inducible systemic deletion of Akt2 enhanced tumour development via elevated circulating insulin levels leading to hyperactivation of AKT1." (PMID 33276499, 2020). "MiR-497 also inhibited tumor growth and suppressed expression of AKT2 at the protein and mRNA levels in mouse xenograft tumors." (PMID 33015042, 2020). "Although the role of AKT2 in human cancer has been well established, the specific mechanism of AKT2-mediated tumor development remains to be explored." (PMID 32873299, 2020). "Taken together, our findings indicated that miR-497 suppresses the tumor growth by targeting AKT2, and the miR-497/AKT2 axis is a potential therapeutic target for NSCLC intervention." (PMID 33015042, 2020).
tumor (continued). "AKT2, characterized as a serine/threonine protein kinase, has been proven to facilitate and contribute to tumor development in addition to its roles in angiogenesis, myoblast differentiation, glucose metabolism and inflammatory disease regulation." (PMID 32873299, 2020). "Present investigation suggested that miR-497 acts as a tumor suppressor, negatively regulates AKT2 oncogene via its 3′-UTR." (PMID 33015042, 2020). "Among these genes, four genes (TIMP1, MAPK13, MAPKAPK2 and MAPKAPK3) are known to regulate cell proliferation, and MMP2 and MMP9 control tumour-associated tissue remodelling; PIK3CD is involved in the immune response, and AKT2 regulates tumourigenesis." (PMID 32999349, 2020). "Higher mRNA levels of AKT2 were found in NSCLC tissues than non-tumor tissues with an inverse correlation between AKT2 and miR-497 expression levels in human tumor samples." (PMID 33015042, 2020). "The results showed that knockdown of AKT2 expression significantly inhibited tumor cell proliferation." (PMID 32873299, 2020). "By using pancreatic cell lines expressing different basal levels of Vav1, we demonstrated here that Vav1 down-regulates the expression of Akt2, known to correlate with tumor metastases and resistance to therapy." (PMID 32993067, 2020). "Under some conditions, AKT2 is suggested to have an inhibitory effect on proliferation and tumor growth, however the role of AKT2 in cell cycle regulation and apoptosis is not as clear as the function of AKT1." (PMID 31752925, 2019). "Aberrantly methylated miR-148a was suggested to function as a tumor suppressor in RCC by targeting AKT2." (PMID 31110513, 2019). "AKT2 has been previously shown to have a direct relationship with malignant transformation and tumor dissemination." (PMID 31357505, 2019). "We focused our attention on AKT2 expression, which was elevated in low attachment growth conditions of mammospheres and in circulating tumor cells." (PMID 31357505, 2019). "We have provided evidence that the inhibition of AKT2 not only affects “bulk” tumor cells, but also inhibits CSC survival in low attachment conditions." (PMID 31357505, 2019). "Of note, we detected a significant increase of AKT2 mRNA expression (FC = 2.3 ± 0.32, p = 0.01) in circulating tumor cells (CTC) isolated from the blood of tumor bearing animals." (PMID 31357505, 2019). "miR-148a targets AKT2, and this interaction leads to the suppression of cell growth, colony formation, migration, and invasion and tumor growth in xenografts." (PMID 31110513, 2019). "In this experiment, animals treated with DEX combined with Akt2 or Akt1/2 inhibitor show significantly reduced tumor size similar to those observed in CCRF-CEM xenograft model." (PMID 30598523, 2019). "In this study we focused on AKT2, since it is the only isoform of AKT associated with EMT and tumor dissemination." (PMID 31357505, 2019). "AKT1 knockdown has an anti-tumor effect, whereas AKT2 ablation can promote tumor growth and AKT3 ablation has little effect." (PMID 31454965, 2019). "Both miR-29c overexpression and cisplatin treatment induce a decrease of ki-67 index and AKT2 expression in xenograft tumor." (PMID 29789623, 2018). "Ablation of Akt1 in the TME generated an inhibitory effect on tumor size, without significant change in animal survival, while elimination of Akt2 or Akt3 resulted in increased tumor size, metastasis, and decreased survival time." (PMID 28929459, 2018). "Activating mutations in AKT1/2 results in accelerated tumorigenesis, however, AKT1 has an inhibitory effect on tumor cell invasion and migration, whereas AKT2 promotes metastasis." (PMID 29720957, 2018). "Human miR-143-3p is known to act as a novel tumor suppressive miRNA by regulating tumor growth, migration and invasion through directly targeting AKT2 gene." (PMID 30619741, 2018). "In summary, this study reports that miR-29c was frequently downregulated in NSCLC and acts as a tumor suppressor gene in NSCLC cells by negatively regulating AKT2." (PMID 29789623, 2018).
tumor (continued). "Previous research demonstrated that miR-29c can target and negatively regulate the expression of the oncogene AKT2 and thus plays a role as a tumor suppressor gene in gastric cancer." (PMID 29789623, 2018). "In contrast to the effect of Akt1- and Akt3-knockdown, Akt2-knockdown significantly stimulated tumor growth." (PMID 29090098, 2017). "Further experiments are needed to deeply elucidate how AKT2 is involved in let-7a -induced tumor suppression." (PMID 29050238, 2017). "Otherwise, in the relatively lower miR-650 expression CRC tumor cells, the inhibition of AKT2 pathway activation is revived." (PMID 28548936, 2017). "Consistent with tumor growth curve, the tumor size and weight of let-7a group were much smaller than that of the control group, and the let-7a+AKT2-overexpression group were partially reversed the inhibitory effect of let-7a." (PMID 29050238, 2017). "The results showed that the average expression levels of AKT2 were significantly higher in tumor tissues than those in the normal tissues." (PMID 29051585, 2017). "Here we describe the mechanisms by which AKT1 and AKT2 play specific roles in tumor growth and dissemination in IBH-6 and T47D human cell lines." (PMID 28287129, 2017). "In agreement with in vitro studies, the levels of AKT2 from the tumor tissues of miR-200c expressing group were lower than that of miR-NC group by immunoblotting assay and qRT-PCR." (PMID 29051585, 2017). "Strikingly, down-regulation of akt-2 or sgk-1, like daf-2, suppressed germline hyperplasia in shc-1;akt-1 animals, indicating that the activity of DAF-2, AKT-2 or SGK-1 in this context contributed to germline tumor formation." (PMID 28549065, 2017). "Taken together, these results suggest that miR-200c inhibits tumor growth through targeting AKT2 in vivo." (PMID 29051585, 2017). "Some of these amplified genes are well-known tumor related genes, such as AKT2, FGFR3, FGF10, SDHA, CCNE1, PI3KCA, and etc." (PMID 28029662, 2017). "Mounting evidence indicates that AKT2 is a crucial mediator in tumorigenesis, tumor progression, metastatic spread and chemoresistance." (PMID 28404925, 2017). "In general, the overexpression of miR-143-3p can suppress tumor growth, migration, and invasion and can promote apoptosis via the targeting of AKT2." (PMID 28404925, 2017). "On day 12 after implantation, tumors from cells overexpressing let-7a were significantly smaller than those from control cells, while the suppression of tumor growth was released in let-7a+AKT2 group." (PMID 29050238, 2017). "In conclusion, our data suggest that miR-143-3p acts as a novel tumor suppressive miRNA by regulating tumor growth, migration and invasion through directly targeting AKT2 gene." (PMID 28404925, 2017). "Many studies showed that miR‐194 is downregulated and functions as a tumor suppressor by downregulating its target genes such as N‐cadherin, AKT2 and BMI1 in a variety of cancers." (PMID 28164432, 2017). "We found that let-7a overexpression significantly suppressed cell proliferation, migration and invasion in vitro and inhibited tumor growth in vivo by targeting AKT2." (PMID 29050238, 2017). "Conversely, tumors developed from Akt2 KD ID8 cells had the highest (p<0.05) tumor cell proliferation, while Akt3 KD tumors had intermediate proliferation." (PMID 27533079, 2016). "In our study, Akt3 knockdown in tumor cells resulted in increased tumor size compared to controls, but to a lesser degree than that seen with knockdown of Akt2." (PMID 27533079, 2016). "Conversely, reducing the effects of Akt2 resulted in increased cell proliferation, accelerated tumor growth and elevated rates of metastasis." (PMID 27533079, 2016).